BCL2 (BCL2 apoptosis regulator)
Diseases named in the same sentence as BCL2 in open-access papers (continued):
Sharing a sentence is not in itself a finding about the gene and the disease.
colorectal cancer (continued). "More importantly, YAP can inhibit autophagy and promote progression of colorectal cancer via upregulating Bcl‐2 expression, while autophagy‐related pathways are enriched and activated in CRC patients and can induce cancer chemoresistance." (PMID 35611809, 2022). "The inhibition of BCL2 expression by hsa-miR-139-5p in colorectal cancer cells increased chemosensitivity." (PMID 36445321, 2022). "In this study, colorectal cancer stem cell-derived exosomes promoted BCL-2, MMP-9 and Vimentin expressions, but inhibited those of E-cadherin, Bax and cleaved caspase-3." (PMID 35470736, 2022). "In HT-29 colorectal cancer cells, Bcl-2 expression was reduced, BAX expression increased, and apoptosis was induced through the PI3K/AKT pathway." (PMID 36142874, 2022). "YAP can inhibit autophagy in human colorectal cancer cells by transcriptionally upregulating Bcl-2, which consequently promotes colorectal cancer progression." (PMID 35606801, 2022). "rhREG4 treatment also protected normal intestinal crypt cells from irradiation-induced apoptosis by enhancing the expression of Bcl-2, Bcl-xL, and survivin, in agreement with data from human colorectal cancer cells." (PMID 36172286, 2022). "Considering the regulatory role of Bax and Bcl-2 genes in the process of apoptosis, these results indicated the increasing anti-proliferative effect of LipGin compared with Gin in a mouse model of colorectal cancer." (PMID 36033959, 2022). "For instance, COX-2 overexpression causes apoptotic resistance in colorectal cancer cells (HCT15 and HT29) by activating Hippo-Yes-associated protein (YAP) and p38/COX-2/PGE2 pathways and inducing Bcl-2 expression." (PMID 35159089, 2022). "Accordingly, lycorine stimulated apoptosis in human colorectal cancer cells in-vitro, as evidenced by the activation of caspase and the increase in the ratio of Bax/Bcl-2." (PMID 35337166, 2022). "ADA promotes apoptosis in colorectal cancer cells via activating the caspase-3 and Bax/Bcl-2 pathways." (PMID 35875119, 2022). "In our current study, we found that GA induced the apoptosis of colorectal cancer cells via Bax, Bcl2, and caspase 3 inhibition, crucial proteins in the mitochondrial apoptosis pathway." (PMID 34747319, 2022). "For example, Western blotting showed that Bcl2 protein levels in colorectal cancer HCT-116 cells were reduced to less than half of the control by 5 days of treatment with 25–100 μg/mL of 3,6-anhydro-L-galactose derived from red seaweed agarose." (PMID 36364387, 2022). "Our results showed that Bcl-2 and Cyclin D1’s expression levels were remarkably decreased in all three colorectal cancer cell lines." (PMID 35879795, 2022). "It has been reported that miR-153-5p promotes the sensitivity of colorectal cancer cells to oxaliplatin through targeting Bcl-2 mediated autophagy pathway." (PMID 36434693, 2022). "For example, overexpression of miR-195 promoted apoptosis in colorectal cancer cell line via targeting antiapoptotic BCL-2." (PMID 35003260, 2021). "For example, STAT3 has been found to be involved in colorectal cancer cell growth, survival, invasion, and migration through regulation of gene expression, such as Bcl-2, p21waf1/cip1, p27kip1, E-cadherin, VEGF, and MMPs." (PMID 34638708, 2021). "On the contrary, an enhanced Bcl-2 level was found in glioblastoma cells, while the expression of Bcl-2 protein was reduced in colorectal carcinoma." (PMID 34770786, 2021). "KRAS‐mutant colorectal cancer was found to be extremely sensitive to combined inhibition of Bcl‐2/Bcl‐xL and mTORC1/2." (PMID 32073727, 2020).
colorectal cancer (continued). "Knockdown of the E3-ligase MARCH5 has been described to sensitize U2OS osteosarcoma as well as HCT116 colorectal cancer cells to the effect of BCL2 inhibition." (PMID 32015503, 2020). "Our results have shown that HM inhibited Bcl-2 and Bcl-xL expression in the human colorectal cancer cell lines." (PMID 32322173, 2020). "It is reported that AST promoted cell apoptosis of the human LS-180 colorectal cancer cell line through the alteration of Bax and Bcl2 expression, and the increase of the expression levels of caspase-3." (PMID 32438569, 2020). "CD276 overexpression, on the other hand, was linked to anti-apoptosis in colorectal cancer through activation of Jak2-STAT3 signaling pathway, and as a result, increased expression of anti-apoptotic protein Bcl-2." (PMID 32188505, 2020). "Bcl-2 and Bcl-x are known as anti-apoptotic proteins, which are highly expressed in colorectal carcinomas." (PMID 32316636, 2020). "MSH6 coexpressed with two DElncRNAs (LOC105374879 and CASC15) and BCL2 coexpressed with B3GALT5‐AS1 were significantly enriched in the colorectal cancer signaling pathway." (PMID 31116002, 2019). "Despite the fact that this gene is generally associated with an oncogenic role and is used as a therapeutic target, in colorectal cancer the increased expression of Bcl-2 is actually a good prognostic factor according to a recent metaanalysis." (PMID 30857282, 2019). "Even though early stages of colorectal carcinoma showed greater frequency of Bcl-2 expression than advanced stages (36.3% versus 28%), however this association was not statistically significant." (PMID 31754362, 2019). "Previous studies have examined the immunohistochemical expression of Bcl-2, an apoptotic marker, in colorectal carcinoma, but results have been contradictory." (PMID 31754362, 2019). "MiR-375 was down-regulated in colorectal cancer (CRC) by inhibiting Bcl-2 pathway control of CRC tumor cells." (PMID 30379973, 2018). "miR-1915 inhibits Bcl-2 to modulate multidrug resistance by increasing drug-sensitivity of human colorectal cancer cells." (PMID 30258285, 2018). "For example, ectopic expression of miR-148a induced apoptosis by suppression of Bcl-2 and activation of a caspase cascade in colorectal cancer cells." (PMID 30510209, 2018). "Quantifying BCL-2 family members in sorafenib HCC therapy, aligns with proposed determinations of mRNA and protein BCL-2 profile as indicative of treatment efficacy in colorectal cancer, lymphoid and myeloid leukemia, among others." (PMID 29682179, 2018). "In this study, we provided a rationale for combined treatment with IDF-11774 and an ATP6V0C inhibitor for patients with colorectal cancer that harbor PIK3CA mutations and thus, exhibit low Bcl-2 expression." (PMID 30420612, 2018). "For example, NF‐Yb knockdown in a colorectal carcinoma cell line (HCT116) induces apoptosis through reductions in the anti‐apoptotic genes Bcl‐2 and BI‐1." (PMID 29704264, 2018). "Overexpression of this gene was shown to confer the resistance to 5-fluorouracil-induced apoptosis in colorectal cancer cells via activation of NF-kappaB and upregulation of BCL-2 and BCL-XL." (PMID 29182684, 2017). "This study aimed to investigate the probiotic characteristics and their ability to inhibit the growth of the colorectal cancer cell line HT-29 with detection of Bax/Bcl-2, LDH and NO." (PMID 28075415, 2017). "Some lactic acid bacteria (LAB) strains have ability to inhibit the growth of the colorectal cancer cell line HT-29 Bax/Bcl-2 pathway or NO production." (PMID 28075415, 2017).
colorectal cancer (continued). "Although the anti-apoptosis protein Bcl-2, which was a direct target of miR-1307, had been reported to be over-expressed in colorectal cancer, we found that ING5 was a target gene of miR-1307 by means of chip analysis and Target Scan software." (PMID 28086946, 2017). "Briefly, one cell proliferation marker, Ki-67 antigen (Ki-67), was upregulated in the cells with overexpressed GAS2, “Correlation between proliferation markers: PCNA, Ki-67, MCM-2 and antiapoptotic protein Bcl-2 in colorectal cancer”." (PMID 27284567, 2016). "We then demonstrated that miR-139-5p inhibits EMT and enhances the chemotherapeutic sensitivity of colorectal cancer cells by regulating BCL2 expression in vitro." (PMID 27244080, 2016). "In conclusion, the present study showed that miR-139-5p is downregulated in colorectal cancer cells and tissues, and its inhibitory effects on cell migration, invasion, and drug sensitivity are mediated by the downregulation of its target BCL2." (PMID 27244080, 2016). "Mechanistically, our study demonstrated that BCL2 is a direct and functional target for miRNA-139-5p in colorectal cancer." (PMID 27244080, 2016). "Previously we have shown that UA inhibited the expression of cell survival proteins survivin and Bcl-2 in a model of orthotopically transplanted human colorectal cancer in nude mice, which supports the findings of our current study." (PMID 26909608, 2016). "We identified BCL2 as a direct target of miR-139-5p in colorectal cancer cells and showed that the tumour suppressor activity of miR-139-5p is mediated by the modulation of BCL2 expression." (PMID 27244080, 2016). "Immunostainings of 190 tumors resected from colorectal cancer patients indicated that PXN expression was positively correlated with Bcl-2, pBcl-2-S87, and MMP2 expression." (PMID 25826088, 2015). "The potential prognostic and predictive significance of Bax and Bcl-2 gene expression and Bax/Bcl-2 ratio were demonstrated in colorectal cancer." (PMID 25864810, 2015). "This study indicates a significant correlation between age and tumor location with Bax/Bcl-2 expression ratio, suggesting predictive value as a potential molecular marker of colorectal cancer." (PMID 25864810, 2015). "It has been additionally reported that the BAX protein expression in neoplasm of the digestive system, including liver and colorectal cancers, is downregulated and conversely, Bcl-2 protein is upregulated." (PMID 25202426, 2014). "Strikingly, we demonstrate a profound impairment of both, migration and invasion, of colorectal cancer cells after Mcl-1, Bcl-2 or Bcl-xL knockdown." (PMID 24098503, 2013). "In summary, our study provides novel insights into the antitumor effects of Bcl-2 protein inhibition in colorectal cancer beyond cell death signaling and cell cycle regulation." (PMID 24098503, 2013). "In turn, Gli is target of translocation or amplification in either breast and colorectal cancers, Bcl2 is amplified in squamous cell lung cancers and the Wnt signaling pathway is altered in of all colon and rectal cancer." (PMID 23922675, 2013). "In several studies over-expression (Cyclin D1, NF-κB, PCNA, MMP-2) or loss of expression (Bcl-2, APC) of these molecules have been found to be associated with more aggressive tumor growth in colorectal cancer." (PMID 23326301, 2013).
colorectal cancer (continued). "ASA has been shown to downregulate anti-apoptotic protein Bcl-2 expression in human prostate adenocarcinoma LNCaP and human colorectal carcinoma CX-1 cells." (PMID 23554697, 2011). "Bcl-2 expression also correlated with a favorable prognosis in colorectal cancer, and with improved overall survival rate in oral squamous cell carcinoma." (PMID 20403207, 2010). "Despite the defined role of Bcl-2 protein in suppression of apoptosis, in colorectal cancer the evidence suggests that Bcl-2 expression is correlated with favourable parameters and a better prognosis." (PMID 16029489, 2005). "In the present study the prognostic value of bcl-2 proto-oncoprotein was immunohistochemically investigated in a series of 104 colorectal carcinomas." (PMID 7547253, 1995). "Notably, rosuvastatin consistently demonstrated superior efficacy in modulating the Bax/Bcl-2 axis across both colorectal cancer cell lines, achieving greater pro-apoptotic shifts at lower concentrations than atorvastatin." (PMID 41596561, 2026). "Moreover, its treatment reduced colorectal cancer proliferation by modulating the NF‐κB pathway and Bax expression while suppressing Bcl‐2, cyclin‐D1, c‐myc, and NLRP3 expression." (PMID 40321606, 2025). "HY0110’s antimicrobial and antioxidant effects surpassed those of LGG, and it exhibited strong antiproliferative activity against HT-29 colorectal cancer cells by attenuating β-catenin and BCL-2 expression while upregulating pro-apoptotic markers P62 and c-PARP." (PMID 40238337, 2025). "In summary, Bcl-xL and Bcl2 are key mediators of apoptosis and may represent promising therapeutic targets for colorectal cancer (CRC) treatment, as demonstrated by our experimental results." (PMID 39940328, 2025). "Similarly, other studies have shown that compounds isolated from S. nervosum, particularly DMC, induce apoptosis in colorectal cancer cells by downregulating Bcl-2 and activating caspase-3-dependent apoptotic signaling." (PMID 40725071, 2025). "These include the induction of ferroptosis in gallbladder cancer via downregulation of GPX4 through the p62-Keap1-Nrf2-HMOX1 axis, as well as the promotion of Bax/Bcl-2 alterations, activation of caspases, and induction of G2/M phase arrest through mitochondrial pathways in colorectal cancer models." (PMID 40978472, 2025). "Furthermore, the downregulation of Bcl-2, an anti-apoptotic gene, was observed in 7k-treated colorectal cancer cells." (PMID 41155994, 2025). "Furthermore, they reported that the increased apoptosis of human colorectal cancer SW480 cells was associated with the increased caspase-3 activity and decreased Bcl-2 expression." (PMID 38286826, 2024). "Also, a recent study described a link between Bcl-2 and YAP, demonstrating that TEAD4 binds to the promoter regions of Bcl-2 and that YAP silencing abrogated downregulated Bcl-2 protein in colorectal cancer cells." (PMID 38755629, 2024).
colorectal cancer (continued). "It was reported that helveticoside represents a promising lead for developing chemopreventive agent against colorectal cancer as it exerted promising in vitro effect by increasing Bax level, inhibiting Bcl-2, and by cleaving caspase-3 and -9, leading to apoptosis." (PMID 39478959, 2024). "Further analysis was conducted via a metabolite–gene–disease interaction network, which illustrated that some of the genes that were tested were directly linked to colorectal cancer in alignment with the metabolites that were found earlier, such as AKT1 and BCL2." (PMID 37233465, 2023). "Increased Bax/Bcl-2 ratio up-regulates caspase-3 and increases apoptosis in many diseases such as in the thymus of patients with myasthenia Gravis, human osteoarthritis, bladder cancer and colorectal cancer." (PMID 36726586, 2023). "In addition, the high expression level of TPM1 enhances the sensitivity of colorectal cancer cells to oxaliplatin via BCL-2 and BAX." (PMID 37854295, 2023). "Ectonucleoside triphosphate diphosphohydrolase 5 (ENTPD5) and BCL2 are proto-oncogenes, the former showing lower expression in colorectal cancer than in normal mucosa, while BCL2 is known to inhibit apoptosis and probably plays a role is the early phases of the adenocarcinoma development." (PMID 36765865, 2023). "Moreover, using focused drug screens, we identified that the BCL-2/Bcl-xL inhibitor ABT-737 was an effective inducer of apoptosis when combined with AZ’1569 in the panel of KRASG12CMT colorectal cancer cells." (PMID 36279564, 2023). "In three studies, probiotics administration reduced Bcl-2 expression while increasing Bax expression, demonstrating that probiotics could inhibit colorectal cancer development in animals by promoting the expression of proapoptotic genes." (PMID 37719797, 2023). "In colorectal cancer, the prognostic significance of BCL2 expression is unclear." (PMID 38067251, 2023). "In vitro and in vivo analyses showed that Azelastine could decrease levels of BCL-2 and inhibit colorectal cancer cell proliferation." (PMID 37193964, 2023). "As a result, the use of 5-FU in combination with Src inhibitors or Bcl-2 antagonists may improve the survival prognosis of colorectal cancer patients." (PMID 37175948, 2023). "Evaluation of Bcl-2 expression in the lamina propria and Bax expression in the epithelium could provide important information for colorectal cancer prognosis as well as potential treatment strategies." (PMID 36013602, 2022). "Furthermore, the bcl-2 inhibitor obatoclax was moderately active when compared to, e.g., colorectal cancer cell lines or bladder cancer." (PMID 36428694, 2022). "It has been observed that KCNQ1OT1 is highly expressed in colorectal cancer cells, and its potential mechanism could act as a sponge for miR-497 (a Bcl-2 inhibitory miRNA)." (PMID 36291546, 2022). "In contrast, overexpression of KCNQ1OT1 could reverse the anti-proliferative function of curcumin and increase Bcl-2 levels to promote cisplatin resistance in colorectal cancer cells." (PMID 36291546, 2022). "Previous studies have indicated that evaluating ratios of Bax and Bcl-2 may provide more useful insights on the prognosis of colorectal cancer, the patient’s lifespan and response to therapeutic drugs." (PMID 36013602, 2022). "Additionally, exosomes derived from CD133+/CD44+ colorectal cancer cells after being transfected with sh-LINC01315 down-regulated BCL-2, MMP-9, and Vimentin, whereas up-regulated Bax, cleaved caspase-3, and E-cadherin in colorectal cancer cells (P < 0.05)." (PMID 35470736, 2022). "In conclusion, the present study provides a novel insight into the role of Bax/Bcl-2 ratios in epithelial–stromal tissues that might have implications in colorectal carcinoma prognosis." (PMID 36013602, 2022). "BCL2 promotes and accelerates metastasis in breast and colorectal cancer." (PMID 34181336, 2021).